NEUROD1 (neuronal differentiation 1)
Diseases named in the same sentence as NEUROD1 in open-access papers (continued):
Sharing a sentence is not in itself a finding about the gene and the disease.
pituitary adenomas (1 paper, 2019). "NeuroD1’s consistently high expression levels in all types of pituitary adenomas make it an attractive potential target for new drugs designed to reduce its expression." (PMID 30719226, 2019). "NeuroD1’s role in the pathogenesis of pituitary adenomas and in the biology of the normal adult pituitary gland has been insufficiently researched." (PMID 30719226, 2019). "In our opinion, NeuroD1’s consistently high expression levels in all pituitary adenoma types make it an attractive potential target for new drugs." (PMID 30719226, 2019). "NeuroD1’s roles in the pathogenesis of pituitary adenomas and in the biology of the normal adult pituitary gland have been insufficiently researched." (PMID 30719226, 2019). "Objective: morphological study of NeuroD1 transcription factor expression in different types of pituitary adenomas and in normal adult human pituitary glands." (PMID 30719226, 2019). "In this study, we performed immunodetection of NeuroD1 in various types of pituitary adenomas." (PMID 30719226, 2019). "Given the fact that NeuroD1 levels are significantly higher in pituitary adenomas than in normal pituitary gland, this protein may be a prognostic factor." (PMID 30719226, 2019). "However, NeuroD1 expression has, in fact, been detected in the null-cell pituitary adenomas." (PMID 30719226, 2019). "In light of NeuroD1’s range of functions, and contradictory data on its expression in pituitary adenomas, it seems plausible to us that its role may not be limited to simply support of corticotroph formation." (PMID 30719226, 2019).
progeria (1 paper, 2023). "Consistently, we found a significant increase in Mbp+ and Cd74+ DAOs in the hippocampus of premature progeria (6-month-old) and 13-month-old mice, whereas the number of NeuroD1-positive post-mitotic neurons decreased in the hippocampus of 13-month-old mice." (PMID 36781874, 2023).
prolactinomas (1 paper, 2019). "NeuroD1 was expressed in the nuclei in all prolactinoma cases." (PMID 30719226, 2019). "Using immunohistochemistry, we have shown that NeuroD1 is expressed not only incorticotropinomas, but in fact in all study samples, including plurihormonal and null-cell pituitary adenomas, prolactinomas, somatotropinomas, mammosomatotropinomas, and gonadotropinomas." (PMID 30719226, 2019). "In prolactinomas, the average numbers of cells expressing given markers were: prolactin 45.8±5.6% (from 40% to 55%); ACTH 0.05±0.08% (0-0.2%); GH 0.03±0.04% (0.04-0.1%); and NeuroD1 98.9±0.6% (98.2-99.3%)." (PMID 30719226, 2019).
schwannoma (1 paper, 2022). A benign, usually encapsulated slow growing tumor composed of Schwann cells. "The authors found that gene transfer of NEUROD1 significantly reduced the proliferation of schwannoma cells." (PMID 36230740, 2022). "Investigators in another study used a variety of transgenic mouse lines to determine how the expression of NeuroD1 affects schwannoma tumor progression, vestibular function, and schwannoma cell proliferation." (PMID 36230740, 2022). "Interestingly, in these intraganglionic schwannoma cells, addition of NeuroD1 induced variable effects, with no overt decrease in schwannoma cell proliferation." (PMID 36230740, 2022).
Sepsis (1 paper, 2020). Sepsis is defined as life-threatening organ dysfunction caused by a dysregulated host response to infection. "We also measured mRNA levels of Neurod1 and Klf4, which were downregulated in the sepsis group, and levels of Tlr2, which were upregulated in the sepsis group." (PMID 33200654, 2020).
small cell neuroendocrine carcinomas (1 paper, 2024). "The lack of apparent NE differentiation is supported by the absence of ASCL1, NEUROD1, and POU2F3, which are all transcription factors associated with small cell neuroendocrine carcinomas, including NEPC." (PMID 38667288, 2024).
spinal cord injury (1 paper, 2022). Penetrating and non-penetrating injuries to the spinal cord resulting from traumatic external forces (e.g., WOUNDS, GUNSHOT; WHIPLASH INJURIES; etc.). "Studies have shown that miR-30a-5p targeting NEUROD1 (encoding neuronal differentiation 1) could improve inflammatory responses and oxidative stress through the MAPK/ERK signaling pathway in cases of spinal cord injury." (PMID 35246136, 2022).
temporal lobe epilepsy (1 paper, 2020). A localization-related (focal) form of epilepsy characterized by recurrent seizures that arise from foci within the temporal lobe, most commonly from its mesial aspect. "Moreover, effective inhibition of neuronal apoptosis provided a neuroprotective effect by the up-regulation of Bcl-2, Bcl2l1, Bdnf, Sox-2, and NeuroD1 genes in an animal model of temporal lobe epilepsy." (PMID 32982679, 2020).
transient cerebral ischemia (1 paper, 2019). "In the present study, a retroviral solution (1.5–2.0 × 107 /ul) of mock pMX-GFP (n = 13) or pMX-Ascl1/Sox2/NeuroD1 (ASN) (n = 14) was directly injected into the ipsilateral striatum and cortex 3 days after 30 min of transient cerebral ischemia." (PMID 31358888, 2019).
tumor (105 papers, 2014 to 2026). "Loss of SMARCA4 function disrupts NEUROD1 expression, leading to changes in tumor differentiation and resistance to therapy." (PMID 40333678, 2025). "Conversely, NEUROD1 has been implicated in promoting tumor growth and metabolic reprogramming in CRC." (PMID 41303610, 2025). "Instead of isolated proteins, we identified a downregulated network of EEC markers (CHGA, GCG, PYY, NEUROD1) associated with tumor processes, reduced survival, and poor chemotherapy responses." (PMID 41303610, 2025). "Our study elucidates the underlying mechanism of ferroptosis in tumor cells, providing a promising novel approach for future therapies by targeting the NeuroD1/GPX4 axis." (PMID 38134213, 2023). "Recent studies have shown that NeuroD1 is highly expressed in various tumor cells and is closely associated with tumorigenesis and poor prognosis." (PMID 38134213, 2023). "Among all genes, four of them—NOTCH1, INSM1, YAP1, and NEUROD1—emerge as the most significant, being associated with both shorter disease-free interval and high tumor stage and/or risk of recurrence." (PMID 36121500, 2022). "Analysis of published patient datasets further revealed that high NeuroD1 expression level correlates with improved overall survival and lower tumor malignancy grade." (PMID 42088619, 2026). "Thyroid hormone-mediated EZH2 inhibition reduces H3K27me3 histone marks at NEUROD1 regulatory regions and enhances NEUROD1 expression, eventually driving tumor cell differentiation into postmitotic cells and suppressing MB growth irreversibly." (PMID 40599851, 2025). "Nonetheless, an analysis of metastatic versus non-metastatic COAD tissue revealed that EEC-related genes (GCG, PYY, CHGA, NEUROD1) were consistently downregulated in both tumor and normal tissue and between metastatic and normal tissue." (PMID 41303610, 2025). "In line with previous studies, 7 of the 14 ASCL1-positive cases were positively stained for both ASCL1 and NEUROD1 to varying degrees, and double-positive cells were distributed in part or the whole of the tumour area." (PMID 40595415, 2025). "Several studies indicate that SOX2 influences the transitions between SCLC subtypes by modulating the expression of ASCL1 and NEUROD1, contributing to tumor heterogeneity." (PMID 41220942, 2025). "In G3-MB, genome-wide chromatin and expression profiling have shown that NEUROD1 acts as a key transcriptional mediator for tumor growth." (PMID 40599851, 2025). "YAP1 expression emerges while ASCL1 and NEUROD1 expression decreases, resulting in a mixed tumour with some YAP1 and ASCL1 expressed side-by-side within the same tumour." (PMID 41290592, 2025). "The remaining 22 samples showed an intermingled expression pattern of ASCL1 and NEUROD1 in the same tumor areas." (PMID 40082639, 2025). "Research employing CODEX and Visium spatial multi-omics technologies demonstrated that tumor regions with a high MPTC signature, characterized by co-expression of ASCL1 and NEUROD1, were linked to poor patient prognosis." (PMID 41220942, 2025). "Conversely, in SHH-MB, mouse models have demonstrated that NEUROD1 overexpression enhances differentiation of tumor cells and inhibits tumor growth." (PMID 40599851, 2025). "Our research revealed that the transcription factor NeuroD1 is able to induce the transdifferentiation of tumor cells into neuron-like cells." (PMID 41225636, 2025). "Consistently, pharmacological inhibition of EZH2 reduces H3K27me3, upregulates NEUROD1, and drives tumor cell differentiation, thereby inhibiting tumor growth." (PMID 40599851, 2025). "We find a striking association between cfDNA accessibility of NEUROD1 inferred from nucleosome footprint analysis and expression of NEUROD1 in the corresponding tumor." (PMID 40001151, 2025). "Co-expression of POU2 F3+/YAP1+ within a tumor has been described as the second most common combination following ASCL1+/NEUROD1+." (PMID 40500731, 2025).
tumor (continued). "Recent molecular analyses of clinical tissue samples demonstrated that NEUROD1 drives epigenetic reprogramming, leading to genetically and epigenetically diverse sub-populations within the same tumor." (PMID 39105169, 2024). "For instance, NEUROD1 promotes tumor cell survival and metastasis in aggressive neuroendocrine lung and prostate tumors by facilitating the transformation of epithelial cells to neuronal-like cells." (PMID 39105169, 2024). "In this study, we uncovered a novel oncogenic function of NeuroD1 as a suppressor of ferroptosis in tumor cells, thereby establishing a link between NeuroD1 and cell death resistance, which is a major hallmark of cancer." (PMID 38134213, 2023). "Using in silico, in vitro, and in vivo analyses, we further revealed the role of NeuroD1 in suppressing tumor cells ferroptosis, and elucidated the molecular mechanism underlying this regulation." (PMID 38134213, 2023). "Knocking down NeuroD1 clearly suppressed the tumor growth rate, as shown by the changes in tumor volume, while overexpressing GPX4 restored it." (PMID 38134213, 2023). "Our results not only link NeuroD1 with tumor cell ferroptosis resistance but also reveal an unprecedented regulatory pathway of ferroptosis." (PMID 38134213, 2023). "The same tendency was also confirmed by tumor morphology, which showed significantly smaller tumors formed by NeuroD1-knocked down HCC-LM3 cells and a clear restoration effect by overexpression of GPX4, as well as by tumor weight." (PMID 38134213, 2023). "NEUROD1 significantly contributes to the promotion of malignant traits, enhancing the survival and migratory abilities of tumor cells, and activates oncogenes such as C-MYC." (PMID 38203275, 2023). "NeuroD1 expression was significantly higher in tumor lesions than in adjacent tissues, and was localized in both cytoplasm and nucleus." (PMID 38134213, 2023). "Recent studies have reported that NeuroD1, first discovered as a neurodifferentiation factor, is upregulated in various tumor cells and plays a crucial role in tumorigenesis." (PMID 38134213, 2023). "Western blotting and immunohistochemical staining confirmed that GPX4 expression was downregulated in the tumor lesions formed by NeuroD1-knocked down HCC-LM3 cells." (PMID 38134213, 2023). "Taken together, these results show that NeuroD1 can increase tumor cell resistance against cell death." (PMID 38134213, 2023). "Together, these results suggested a positive correlation between NeuroD1 and GPX4 in tumor tissues, further confirming the possible regulation of NeuroD1 on GPX4 as obtained by cellular experiments." (PMID 38134213, 2023). "While the NE PDX models show a mutually exclusive expression of ASCL1 and NEUROD1, human NE tumors were found to exhibit a complex tumor structure with subtypes co-existing as separate sub-populations within the same tumor." (PMID 36711033, 2023). "Together, our findings reveal NeuroD1 as a crucial ferroptosis suppressor gene, thereby unraveling a novel mechanism of tumor cells ferroptosis resistance." (PMID 38134213, 2023). "Molecular studies using human SCLC (hSCLC) cell lines showed that ASCL1 and NEUROD1 are required for the survival of the cells’ increased tumor-initiating capacity in xenograft assays suggesting that these factors lead to similar cellular consequences." (PMID 36428693, 2022). "NEUROD1 was significantly downregulated in tumor samples compared with para-tumor samples and most tumor samples lowly expressed NEUROD1." (PMID 36313290, 2022). "The authors concluded that NeuroD1 inhibits the proliferation of Schwann cells and functions as a tumor suppressor." (PMID 36230740, 2022). "NEUROD1 expression levels had a strongly correlation with infiltrating levels of PDL1+ tumor (r = -0.200, P = 0.035)." (PMID 35311069, 2022). "The ASCL1 and NEUROD1 staining showed intra-tumoral heterogeneity that defined two separated tumor populations, which are present at different foci across the tumor section." (PMID 34599169, 2021).
tumor (continued). "According to a recent study, MYC can act as a master regulator for NE-differentiation and can dynamically shift tumor phenotype acting on the NOTCH signaling pathway from ASCL1 + NEUROD1+ (NE-high) to YAP1+ or POU2F3+ (NE-low)." (PMID 34200100, 2021). "Meta-program C was defined by many markers of differentiated GNs including Neurod1 and Nhlh1, probably reflecting the differentiation states of tumor cells." (PMID 34210306, 2021). "A recent study demonstrates that NEUROD1 exerts its oncogenic transcription factor role in maintaining tumor enhancer landscape of G3-MB in cooperation with OTX234." (PMID 33268769, 2020). "NeuroD1 expression was observed not only in the vast majority of tumor cells, but also in vascular cell nuclei." (PMID 32064038, 2020). "A panel of neuronal genes, such as DCX, NEURONG2, MAP2, NEUROD1, were upregulated with FTT treatment for 2 or 10 days, while tumor associated genes downregulated." (PMID 30837577, 2019). "Bioinformatics analysis of TCGA data revealed that the expression levels of a panel of neuronal genes in GBM were significantly lower than those in non-tumor tissues, and patients with high NEUROD1 or MAP2 expression had a better outcome." (PMID 30837577, 2019). "With the passage of time, it seems likely that tumor cells change into an ASCL1 (low)/NEUROD1 (high) expression pattern which is coincident with the appearance of variant morphology phenotype in GEMMs." (PMID 30477547, 2018). "The effect on tumor cell growth is likely to be due to both a decrease in cell proliferation (Ki67 and BrdU markers) and an increase of cell differentiation (NeuroD1 and NeuN markers)." (PMID 29538458, 2018). "Neurod1 contributes to the differentiation of adrenocorticotropic hormone (ACTH)-secreting tumours and gonadotroph tumours (GT)." (PMID 29979686, 2018). "In particular, we examined the expression of some neuroendocrine markers and a marker of neuronal differentiation, NeuroD1, whose expression can help to better understand the nature of this neoplasia." (PMID 24621010, 2014). "Highly differentiated tumor cells exhibited elevated NeuroD1 expression." (PMID 41225636, 2025). "IHC analysis revealed divergent ASCL1 and NEUROD1 expression in discrete tumor foci." (PMID 38645034, 2024). "The Osimertinib-resistant tumor showed upregulation of NEUROD1 expression." (PMID 39456595, 2024). "Similarly, our study concerning the analysis of our scRNA-seq in metastatic SCLC also identified the different ASCL1 and NEUROD1 expression patterns, which further uncovered the diversity of inter-patient and intra-tumor heterogeneity." (PMID 39103941, 2024). "However, the role of NeuroD1 in tumorigenesis and its potential involvement in tumor cell death resistance are not yet fully understood." (PMID 38134213, 2023). "ASCL1 and NEUROD1 regulate different genes, but ASCL1 is the leading cause of tumour formation." (PMID 37870696, 2023). "Our previous study also revealed that NeuroD1 could promote tumor cell metabolic reprogramming, as it could enhance the pentose phosphate pathway (PPP) by promoting the transcription of the PPP rate-limiting enzyme G6PD." (PMID 38134213, 2023). "Additionally, dCas9-TAD-VPR led to the up-regulation of tumor-related genes like NEUROD1 and HNF4, all in response to hypoxia." (PMID 37798384, 2023). "Moreover, tumour-associated CD8 + T cells are interconnected with molecular subtype; the non-ASCL1/NEUROD1 subtypes have significantly more CD8 + T cells than those of the ASCL1/NEUROD1 subtypes, thus they can benefit more from immunotherapy." (PMID 37870696, 2023). "Together, these data indicate the negative regulation of NeuroD1 in tumor cell ferroptosis." (PMID 38134213, 2023). "It was speculated that the shift to NEUROD1-high expression in tumor cells surviving concurrent chemoradiation therapy may be related to the poor outcome after combined modality treatment." (PMID 37253435, 2023). "Both ASCL1 and NEUROD1 were expressed in the nuclei of tumor cells." (PMID 35220975, 2022).